PLK1 (polo like kinase 1)
Diseases named in the same sentence as PLK1 in open-access papers (continued):
Sharing a sentence is not in itself a finding about the gene and the disease.
tumor (continued). "I2 was therefore selected for further experiments to identify its active analogs, and to determine its ability to inhibit tumor growth in vivo and PLK1 enzymatic activity." (PMID 23658603, 2013). "Systemically injected Her2ab/Plk1 siRNA nanoparticles were localized to Her2 expressing cells in xenografts and persisted for more than 72 hours, leading to Plk1 gene silencing and tumor cell apoptosis." (PMID 23667320, 2013). "A better understanding is required to maximize efficacy and minimize side-effects of combined Plk1 therapy in terms of administration schedules, such as succession and dosage, in each individual tumor." (PMID 23948487, 2013). "Plk1 strongly promotes progression of the cell cycle and is responsible for aggressive proliferation of tumor cells, regarded as a cellular proliferation marker." (PMID 23948487, 2013). "Compared to previously published data, we noted that ON-01910 had lower activity of inhibiting tumor cell growth and Plk1 enzymatic activity in our experiments." (PMID 23658603, 2013). "Several clinical trials of the Plk1 inhibitor BI 2536 have been performed in different tumor types and the mono-therapy of Plk1 inhibitors has shown modest efficacy, suggestive of combined strategy." (PMID 23948487, 2013). "Recent studies suggest that targeting PLK1 with small molecule inhibitors is a promising approach to tumor therapy." (PMID 22390279, 2012). "We conclude therefore that PLK1 plays a key role in regulating stem-like characteristics of tumor cells." (PMID 22390279, 2012). "So, it can be demonstrated that miR-100 negatively regulated PLK1 at the post-translational level, acting as a tumor suppressor in the EOC." (PMID 22246341, 2012). "It will be important to elucidate in detail the specific mechanisms by which PLK1 mediates tumor-initiating cell growth." (PMID 22390279, 2012). "PLK1 promotes tumor cell proliferation and cell transformation, thus, it is a new target for antitumor therapy." (PMID 23226764, 2012). "The overexpression of PLK1 has been reported to play critical roles in malignant transformation and tumor development." (PMID 23151088, 2012). "We found that RNAi-mediated inhibition of PLK1 mRNA in tumor spheres significantly decreased SOX2 mRNA expression compared to control transfected cells with no significant change in NES, Nanog, and c-Myc mRNA expression." (PMID 22390279, 2012). "Since PLK1 is associated with the incidence, development and prognosis of tumors, the role of PLK1 activity suppression in tumor therapy and prognosis has become the focus of research." (PMID 23226764, 2012). "Whereas most studies used immunohistochemistry to analyze Plk1 expression, a few studies also used RT-PCR to measure mRNA of Plk1 in human tumor samples." (PMID 23227884, 2012). "In general, overexpression of Plk1 is typically considered to be oncogenic in nature while the remaining Plks likely function as tumour suppressors." (PMID 21324136, 2011). "In contrast, we discovered the opposite correlation for Plk1 where in normal liver tissue the Plk1 promoter is hypermethylated while in tumours, Plk1 CpG islands become hypomethylated and the gene upregulated." (PMID 21324136, 2011). "Intriguingly, overexpression of PLK1, the human homolog of CDC5, has been reported in various tumor types and has been linked to poor prognosis." (PMID 20126259, 2010). "Overexpression of Plk1 correlates positively with tumor stage, nodal status, and diffuse growth pattern in human gastric cancer." (PMID 19216791, 2009). "Subsequently, we tested other anti-mitotic agents: BI2536 is a potent and specific inhibitor of the mitotic kinase Plk1 and inhibits tumor growth in vivo." (PMID 19243593, 2009). "Surprisingly, 30% of Plk1 heterozygous mice developed tumors at an average of 13–14 months old, and this was a 3-fold increase of tumor incidence compared with that in wild type mice." (PMID 19161615, 2009).
tumor (continued). "Silencing PLK1 expression by RNA interference inhibits tumor cell proliferation and induces G2/M arrest." (PMID 19775446, 2009). "For example, intravenous injection of Plk1 ASO significantly suppressed growth of A549 cells in tumor xenografts." (PMID 19161615, 2009). "Of the 36 tumor sections, 32 showed positive immunostaining for PLK-1, with a positive rate of 88.9%." (PMID 19775446, 2009). "A cohort of Plk1 wild type and heterozygous mice were maintained and the tumor development was monitored." (PMID 19161615, 2009). "It is of note that the S–G2–M progression markers, Aurora A and Plk1, were identified as particularly powerful independent prognostic markers, in keeping with their higher expression levels in actively cycling tumour cell populations." (PMID 19240714, 2009). "Because of this, these mitotic kinases including Plk1 are often considered as proto-oncogenes, whose overexpression is often observed in tumor cells." (PMID 19161615, 2009). "Multiparameter analysis of Mcm2–7, geminin, Aurora A, Plk1 and H3S10ph, core regulators of the G1–S and G2–M transitions, thus allows a detailed analysis of the kinetics of complex dynamic tumour cell populations." (PMID 19240714, 2009). "Again, the similar tumor phenotypes of Plk1 and Aurora A heterozygous mice suggest that balanced mitotic kinases are important for maintaining genomic stability." (PMID 19161615, 2009). "To evaluate the possible importance of PLK-1 in tumor progression, we then evaluated the relationship between PLK-1 intensity and tumor size." (PMID 19775446, 2009). "In earlier studies, we and others found PLK1 overexpressed in a variety of tumours, compared to the respective corresponding tissue of origin, suggesting an important role of high levels of PLK isoenzymes for tumour growth." (PMID 14970859, 2004). "We investigated the HPA immunohistochemistry and DepMap CRISPR screenings to confirm the tumor-intrinsic essentiality of PLK1 and AURKA, while utilizing the TISCH single-cell dataset to validate the microenvironmental specificity of CTLA4 (T-cells) and PPARG (CAFs/Macrophages)." (PMID 41596281, 2026). "Furthermore, transcriptomic profiling indicated a significant correlation between high PLK1 expression and an immunosuppressive tumor microenvironment." (PMID 41556056, 2026). "Moving forward, we propose exploring a three-drug combination regimen involving FGFR inhibitors, osimertinib, and PLK1 inhibitors, which might more effectively eradicate residual tumor cells and promote tumor regression." (PMID 41539998, 2026). "Our study establishes a correlative, rather than causal, link between PLK1 overexpression and an immunosuppressive tumor microenvironment (TME), as inferred from transcriptomic analyses." (PMID 41556056, 2026). "Consequently, in PC-3 xenografts, the PLK1 mRNA expression was reduced by 77% and tumor growth was suppressed by 84.3%." (PMID 40756358, 2025). "Our work demonstrates that different 14-3-3 paralogs regulate different steps in the centrosome cycle and that disrupting complex formation between 14-3-3ε and Plk1 or separase could be a novel therapeutic strategy in tumor cells." (PMID 40576425, 2025). "By inhibiting PLK1, these combinations can address the issue of drug resistance to certain chemotherapy agents and act as radiation sensitizers, thereby enhancing the effectiveness of tumor chemoradiotherapy." (PMID 40612941, 2025). "Importantly, pharmacological inhibition of PLK1 effectively abrogated TRIM47-driven tumor growth in xenograft models." (PMID 41460629, 2025). "Given that CIN is a key contributor to tumor heterogeneity, and that PLK1 overexpression is known to induce CIN in tumor cells, we aimed to identify which of the 65 SDL hits we validated selectively impact the survival of PLK1-overexpressing cells at a single-cell resolution." (PMID 40347943, 2025). "Our study demonstrated that USP10 acted as a tumor promoter and deubiquitinated PLK1 in PDAC." (PMID 40517136, 2025).
tumor (continued). "To further evaluate the therapeutic potential of IGF2BP2 inhibition, we examined whether C4 treatment reduced tumor development in PLK1-high xenograft and PDX models of TNBC." (PMID 40347943, 2025). "As a result, combinatorial approaches that integrate telomerase inhibition with other targeted therapies, such as Polo-like kinase 1 (PLK1) inhibitors, may be necessary to achieve sustained tumor control in HCC." (PMID 40243493, 2025). "Importantly, various tumor tissues display overexpression of PLK1, which has been correlated with poor prognosis." (PMID 41300524, 2025). "Instead, we used a single-cell CRISPR screen to identify the most optimal SDL hits that could overcome tumor heterogeneity in the context of PLK1 overexpression." (PMID 40347943, 2025). "Conversely, Plk1 depletion markedly delayed tumor formation and progression." (PMID 41284701, 2025). "Additionally, comparative analysis of the integrated plk1-mediated genomic instability circuits with transcriptomic data from different tumor types showed widespread impacts on the expression patterns of the three identified circuits." (PMID 40430225, 2025). "Since we had demonstrated that TRIM47 promoted LC proliferation by stabilizing PLK1 through ubiquitination in vitro, we then intended to explore whether the regulatory mechanism was the same in the tumor xenograft model." (PMID 41460629, 2025). "Stage-specific analysis further identified key drivers of distinct disease transitions including EZH2 and PLK1 as major regulators of androgen dependence in mHSPC, and TERT as a hallmark of mCRPC, highlighting its role in telomere maintenance and tumor progression." (PMID 41402347, 2025). "Furthermore, microarray analysis of PLK1-TD expressing cells identified that the immune system process plays a key role in the tumor microenvironment." (PMID 40860188, 2025). "The levels of PRC1 and PLK1 in tumor cells were detected by IHC to explore whether the sensitization effect of B4 for cisplatin was due to the inhibition of PLK1/PRC1 signaling pathway." (PMID 40355412, 2025). "However, PLK1 as a target of direct immunotherapy still faces multiple challenges, mainly involving target specificity, immunogenicity and tumor heterogeneity." (PMID 40612941, 2025). "Although PLK1 inhibitors combined with paclitaxel or PARPi have synergistic effects in inhibiting tumor cell growth in preclinical models of EOC, there are currently no reports on the combination of PLK1 inhibitors with other chemotherapeutic drugs in clinical trials of EOC." (PMID 41458961, 2025). "Blocking the expression of PLK1 can inhibit the proliferation of tumor cells and induce apoptosis." (PMID 40615690, 2025). "The expression level of PRC1 may serve as a predictive biomarker for the anti-tumor effectiveness of PLK1 inhibitors, further underscoring the importance of PRC1 research in clear ccRCC." (PMID 40093809, 2025). "I.v. injection into tumor‐bearing mice led to editing of the PLK1 gene and reduced tumor burden." (PMID 39263835, 2025). "In addition, we also analyzed PLK1 expression in A549 tumor models after the treatment of B4 and cisplatin by IHC." (PMID 40355412, 2025). "However, emerging evidence suggests that PLK1 can also function as a tumor suppressor in specific contexts." (PMID 41261855, 2025). "By aerosolizing the nanoparticle, the researchers observed that they could accumulate in the lungs and silence the expression of beta III-tubulin and Polo-Like Kinase 1 (PLK1) in lung tumors in mice, which delays tumor growth." (PMID 40487670, 2025). "Meanwhile, in vivo experiments confirmed that PLK1 inhibitor combined with PD-L1 inhibitor could significantly reduce tumor progression in mice compared with the two drugs alone." (PMID 40612941, 2025). "Therefore, TAM polarization is promoted in TSG6-upregulated cells driven by active PLK1 within the tumor microenvironment." (PMID 40860188, 2025).
tumor (continued). "To explore whether PLK1 participates in tumor therapy resistance, we analyzed the impact of PLK1 expression on the survival of patients receiving chemotherapy or radiation therapy." (PMID 40355412, 2025). "Biomarkers influencing the sensitivity of tumor cells to PLK1 inhibitors." (PMID 41458961, 2025). "PLK1 inhibitors could induce p21 increased, and long-term treatment with PLK1 inhibitors induced senescence of tumor cells with functional p21." (PMID 40896432, 2025). "Similarly, inhibition of PLK1 in vivo effectively attenuated TRIM47-mediated tumor promotion in xenograft models." (PMID 41460629, 2025). "The inhibition of p-PCTP by PLK1 in tumors was stronger by PR00012 treatment in tumor-bearing mice." (PMID 40190550, 2025). "Studies have shown that PLK1 is a key regulator of EMT in tumor cells." (PMID 40612941, 2025). "Extensive clinical and pathological data proposes that PLK1 signaling plays a key role in tumorigenesis and may serve as a potential biomarker for tumor progression." (PMID 39451218, 2024). "Interestingly, half of the genes analyzed, namely, BIRC5, TOP2A, PLK1, and RRM2, were associated with lung-specific neoplasms." (PMID 39596028, 2024). "In this study, we initially established that PLK1 is markedly overexpressed in CRC tumors from individuals of Arab descent, with its overexpression associated with several aggressive characteristics, including larger tumor size and an advanced stage." (PMID 39451218, 2024). "Here, using genetically engineered mouse model and single-cell RNA-seq analysis, we report that PLK1 promotes an immunosuppressive TME in LUAD, characterized with enhanced M2 polarization of tumor associated macrophages (TAM) and dampened antigen presentation process." (PMID 38885192, 2024). "Treatment with the PLK1 inhibitor volasertib (25 mg/kg) suppressed tumor growth." (PMID 38057358, 2024). "Therefore, inhibiting PKMYT1 not only leads to suppression of tumor growth by regulating its own expression, but also exhibits an additional unexpected inhibitory effect through PLK1 regulation." (PMID 38570712, 2024). "In addition, a combination of BRD4 and PLK1 inhibitors showed synergistic anti-tumour effects in paediatric tumour models including RMS that is associated with MYCN-driven gene expression." (PMID 38191874, 2024). "Recent studies have revealed that PLK1 might play as a tumour‐suppressor gene, and limited preclinical achievements of PLK1 inhibitors have been translated into good clinical outcomes." (PMID 38887977, 2024). "In CCA, the PLK1 inhibitor BI-2536 repressed CCA tumor growth." (PMID 38057358, 2024). "The interaction between EXO1 and PLK1 may facilitate enhanced cell proliferation and survival, thereby contributing to tumor aggressiveness." (PMID 39777332, 2024). "PLK1 is regarded as a promising target for the development of anti-tumor drugs." (PMID 38393054, 2024). "PLK1 overexpression was noted in 60.3% (693/1149) of CRC cases and was significantly associated with larger tumor size (T3/T4 tumors; p = 0.0086), lymph node metastasis (<0.0001), Stage III tumors (p = 0.0008), deficient mismatch repair (dMMR) status (p = 0.0416)." (PMID 39451218, 2024). "While these results suggest that PLK1 may be an important modulator of tumor immunity, whether and how PLK1 functions in the TME of LUAD is largely unknown." (PMID 38885192, 2024). "Given that both the CDKs family and PLK1 control tumor cell survival and progression by regulating cell cycle, a reasonable speculation is that CDKs inhibitors may also have an enhanced ferroptosis inducers sensitivity effect similar to BI2536." (PMID 38536443, 2024). "More importantly, PLK1 expression was shown to be particularly increased in TNBC compared to other subtypes, and increased TNBC tumor grade (poorer differentiation and increased genome instability, leading to aggressive tumor growth) correlates with the expression level of PLK1." (PMID 39524172, 2024).
tumor (continued). "PLK1 KO led to a dramatic reduction in tumor size and a decrease in lung metastasis rate." (PMID 37419907, 2023). "This suggests that the combined inhibition of UBE2C and PLK1 may more significantly suppress tumor progression by inducing cell cycle arrest and apoptosis than either of them alone." (PMID 37958642, 2023). "Previous studies have shown that Plk1 inhibits or promotes autophagy in tumor cells." (PMID 37640723, 2023). "Interestingly, a global Plk1-overexpression murine model demonstrated that Plk1 overexpression promotes chromosomal instability, contributing to aneuploidy and spontaneous tumor formation." (PMID 37174744, 2023). "PLK1 expression was significantly higher in the tumor samples in TCGA-BRCA cohort." (PMID 38186570, 2023). "PLK1 expression was increased in tumour tissue compared with matched non-tumour liver (P < 0.0001)." (PMID 37648284, 2023). "Therefore, considering our bioinformatic findings, we propose that PLK1 affects the level of immune infiltration in LA through necroptosis, ultimately affecting tumor proliferation." (PMID 37744268, 2023). "However, PPI networks revealed a very complex protein network between these components, making it impossible to discern the regulatory functions of PLK1 in tumor immunostimulation and immunosuppression." (PMID 36951624, 2023). "Therefore, PLK-1 is considered a more promising and attractive target for anti-tumor drug design due to its better safety profile." (PMID 36985522, 2023). "PLK1 inhibitor BI 2356 shows strong anti-tumor activity in NB cells in vitro and in vivo." (PMID 36770809, 2023). "In the genomic analysis of LUAD, the levels of CTNNB1 were higher in patients with metastatic stages 3 and 4 (46%, 7 tumors/15 total) than in those with tumor stage 1 (27%; 8 tumors/29 total), indicating that β-catenin and PLK1 are markedly expressed in metastatic NSCLC, especially in LUAD." (PMID 36793862, 2023). "In addition, PLK1 expression level, age and the tumor stage were identified as independent prognostic markers for BRCA." (PMID 38186570, 2023). "Even so, Plk1 inhibitors have attracted controversy as to whether they are effective and safe anti-tumor agents." (PMID 36845678, 2023). "PLK1 is frequently upregulated in majority of human tumors including GBM but not in normal cells; furthermore, increased levels of PLK1 and its activity are associated with tumor progression and poor prognosis." (PMID 36805592, 2023). "And PLK1 may have a role in promoting tumor proliferation by reducing the level of LA immune infiltration through inhibition of necroptosis." (PMID 37744268, 2023). "Additionally, we found that hub genes identified through PPI analysis were predominantly members of the GAGE gene family, which primarily functions in anti-apoptosis and tumor metastasis, indicating a potential antagonistic effect of PLK1 in necroptosis." (PMID 37744268, 2023). "Tumors collected at the end of the experiments showed that M1-21 significantly decreased the size and weight of engrafted tumors compared to controls, correlated with the decreased levels of FOXM1 and FOXM1-regulated CDC25B and PLK1 in M1-21-treated tumor samples." (PMID 37344857, 2023). "The results showed that the absorbance of A549 and H1299 cell lines in the overexpression group was significantly increased (p < 0.001) at 24, 48 and 72 H compared with the cells in the normal group, suggesting that tumor cells proliferated significantly after overexpression of PLK1." (PMID 37744268, 2023).